MMP2 (matrix metallopeptidase 2)
Diseases named in the same sentence as MMP2 in open-access papers (continued):
Sharing a sentence is not in itself a finding about the gene and the disease.
rhabdomyosarcoma (8 papers, 2013 to 2022). A rare aggressive malignant mesenchymal neoplasm arising from skeletal muscle. "For instance, the more aggressive alveolar rhabdomyosarcoma presents higher protein levels of both MMP14 and MMP2 than the embryonal rhabdomyosarcoma type, where both these proteases are often undetectable." (PMID 31466240, 2019). "Moreover, aspirin abolished FN-induced MMP2 upregulation in rhabdomyosarcoma cells through the COX-2 and PGE2 pathways." (PMID 36558974, 2022). "Rhabdomyosarcoma showed MMP-2 and faint MMP-9 bands; PMA treatment enhanced MMP-9 expression." (PMID 23900236, 2013).
skin aging (8 papers, 2015 to 2025). The gradual irreversible changes in structure of skin that occur as a result of the passage of time.. "Future investigations into the effects of PNA-20 CEF that can also inhibit the activities of other MMPs involved in photoaging, including MMP-2, -3, and -9, would be useful to generate additional products against skin aging." (PMID 37048555, 2023). "On the other hand, PM2.5 has been shown to induce MMP-2 and MMP-9 expression in human keratinocytes and cause skin aging." (PMID 32922544, 2020). "In addition, PM-induced oxidative stress promoted via the production of ROS and subsequent increase in the activity of matrix metalloproteinases (MMPs), including MMP-1, MMP-2, and MMP-9, can cause skin aging as a consequence of the degradation of collagen." (PMID 30669248, 2019). "Moreover, the flower extract also inhibited collagenase, MMP-2 and tyrosinase activity, all of which are involved in skin aging." (PMID 27912751, 2016). "First, harringtonine markedly suppressed the expression of matrix metalloproteinases (MMP-1, MMP-2, and MMP-9), which are critical mediators of ECM degradation and play central roles in the pathogenesis of skin aging and photoaging." (PMID 40864795, 2025). "In skin aging models, MMP-1 and MMP-2 levels were reduced after application of all tested substances." (PMID 36838716, 2023). "The accumulation of ROS has been reported to induce skin aging through the expression of MMPs, including MMP-1, MMP-2, and MMP-9." (PMID 30669248, 2019). "Through the MAPK signaling pathways, AP-1 controls the expression of MMPs, especially MMP-1, MMP-2, and MMP-9, in inflammation-induced skin aging." (PMID 28900534, 2017). "As MMP-2 and MMP-9 have also been reported to be involved in skin aging through the degradation of collagen, we analyzed the expression levels of MMP-2 and MMP-9 protein and found that these were also increased by PM2.5 treatment and decreased by FFO pretreatment." (PMID 30669248, 2019). "Indeed, we detected a set of metallo-proteinases (MMP2, MMP14), collagens (e.g. COL6A1, COL3A1, COL5A1 and others) and elastin (ELN), which showed a significant longitudinal change in expression in addition to being closely correlated to skin aging." (PMID 25977295, 2015).
thrombosis (8 papers, 2016 to 2025). "Specifically, the MMP-1 rs1799750 and MMP-2 rs243865 polymorphisms were significantly associated with an increased risk of venous thrombosis (p = 0.041 and p = 0.022, respectively)." (PMID 40724896, 2025). "Multiple studies have confirmed the role of MMP-1 and MMP-2, along with inflammatory factors, in the pathogenesis of deep vein thrombosis." (PMID 40724896, 2025). "ABPPk possesses the capability to inhibit the infiltration of polymorphonuclear leukocytes (PMNs) and the activation of matrix metalloproteinase-2/-9 (MMP-2/-9), thus effectively reducing the occurrence of thrombosis." (PMID 37728585, 2024). "Study showed that miR-205 directly targeted PTEN, regulated Akt/autophagy pathway and MMP2 expression, and played a key role in the function of endothelial progenitor cells (EPCs), deep vein thrombosis (DVT) recanalization and regression." (PMID 33546692, 2021). "For example, it has been shown in mice that MMP‐2 amplifies the response of platelets to weak stimuli, thereby promoting arterial thrombosis and that this process can be abolished by infusion of TIMP‐2." (PMID 33107073, 2021).
acute lymphoblastic leukemia (7 papers, 2000 to 2025). Leukemia with an acute onset, characterized by the presence of lymphoblasts in the bone marrow and the peripheral blood. "Earlier reports show an association of MMP-2/-9 expression with invasive behaviour of leukemic cells in acute lymphoblastic leukemia (ALL) and acute myelogenous leukemia (AML)." (PMID 21857898, 2011).
ascending aortic aneurysms (7 papers, 2015 to 2026). "Serum MMP-2 levels could be associated to ascending aortic aneurysms in a previous study and we found, that serum MMP-2 levels for patients with ascending aortic aneurysms significantly lower than serum levels in healthy controls (190.3 +/- 48.3 ng/ml vs 240.3 +/- 46.4 ng/ml)." (PMID 27802285, 2016). "Application of LASSO-LR analysis revealed age, plasma MMP-2, and peak aortic valve velocity (Vmax AV) as independent factors influencing ascending aortic dilation in BAV patients." (PMID 42290966, 2026). "All tissue protein extracts taken from ascending aortic aneurysms contained considerable amounts of the 72kDa pro-MMP-2." (PMID 27802285, 2016). "In the tissue samples taken from aortic tissue from patients with ascending aortic aneurysms, we observed a second gelatinolytic activity at a molecular weight of approximately 65 kDa, where the active MMP-2 is known to run." (PMID 27802285, 2016). "In another study, plasma levels of MMP-2 were found to be lower in patients with ascending aortic aneurysms." (PMID 27802285, 2016). "Pro- and active MMP-2 were measurable in protein extracts from patients with ascending aortic aneurysms with bicuspid aortic valves and in patients with ascending aortic aneurysms and tricuspid aortic valves." (PMID 27802285, 2016). "Taken together, this indicates, that MMP-2 alone is an unsuitable marker for a common measurement of high wall stress in ascending aortic aneurysms." (PMID 27802285, 2016). "We also noted considerable amounts of active 65 kDa MMP-2 in all tissue extracts from patients with ascending aortic aneurysms tested." (PMID 27802285, 2016). "Our finding, that patient sera contained slightly lower MMP-2 amounts than control sera is in line with that complexity Our results differ from previous findings, where MMP-2 plasma levels were elevated in association with ascending aortic aneurysms." (PMID 27802285, 2016). "Therefore further investigation is required to discover whether there are different MMP-2/TIMP interactions in the serum of patients with ascending aortic aneurysms versus healthy controls." (PMID 27802285, 2016). "We observed, that pro-MMP-2 (72 kDa) and active MMP-2 (65 kDa) were detectable in all of our tissue samples taken from patients with ascending aortic aneurysms–irrespective of aortic valve configuration or other clinical parameters." (PMID 27802285, 2016).
atrial fibrillation (7 papers, 2011 to 2024). A disorder characterized by an electrocardiographic finding of a supraventricular arrhythmia characterized by the replacement of consistent P waves by rapid oscillations or fibrillatory waves that vary in size, shape and timing and are accompanied by an irregular ventricular response. "MMP2 has previously been suggested as a candidate gene in MRONJ, as BPs are associated with atrial fibrillation, and MMP2 is associated with both bone and cardiovascular abnormalities." (PMID 39408816, 2024). "In patients with atrial fibrillation, higher baseline plasma MMP-2 levels were independently associated with cardiovascular events or death during a mean follow-up of 28 months." (PMID 28446168, 2017). "Recently, alterations in the expression of Timp2 and Mmp2 have been shown to be associated with atrial fibrillation in different respects, with the latter enriched in left atrium in two out of three of our datasets." (PMID 22039477, 2011). "The relationship between MMP-2 and incident atrial fibrillation modeled by quintiles, ARIC 1990–2007." (PMID 23554968, 2013). "Exclusion of individuals with atrial fibrillation did not change the results, except for the association of serum MMP-2 levels with Ln LA volume index, which was attenuated." (PMID 32668720, 2020). "Yet, most studies were done in selected populations (e.g., patients with heart failure, atrial fibrillation or primary aldosteronism), reported on a single MMP (i.e., MMP-2, MMP-9 and TIMP-1) and did not adjust for potential confounders." (PMID 32668720, 2020).
cataract (7 papers, 2008 to 2024). Partial or complete opacity of the crystalline lens of one or both eyes that decreases visual acuity and eventually results in blindness. "Matrix metalloproteinase-2 (MMP-2) polymorphisms have been considered as risk factors of cataracts, but the results still remain controversial." (PMID 33832130, 2021). "In this study, PEDF levels in the aqueous humor in cataract patients were lower and MMP-2 and TGF-β2 levels were higher, indicating abnormal changes in PEDF, MMP-2, and TGF-β2 levels in the aqueous humor in cataract patients." (PMID 39413500, 2024). "Increased TIMP levels were observed in the aqueous humor of patients with cataracts, possibly to compensate for the elevated level of MMP-2." (PMID 35457074, 2022). "Since the expressions of matrix metalloproteinases (MMPs) are part of the EMT process, we performed a Western blot to determine the protein levels of MMP2, since we previously showed that MMP2 mRNA expression was increased in transgenic mice cataracts." (PMID 29888254, 2018). "Compared with the cataract group, the concentration of IL-8, MMP-2, MMP-3, MMP-9, TGFβ-1, TGFβ-3, and TNF-α was significantly increased in subjects with JIAUwG or JIAUwoG." (PMID 29675026, 2018). "We have further shown that TGFβ-induced cataracts can be mitigated through inhibition of the matrix metalloproteinases (MMP) MMP-2 and MMP-9." (PMID 23559862, 2013). "PEDF was lower and MMP-2 and TGF-β2 were higher in the aqueous humor of cataract patients than that of healthy subjects (p < 0.05)." (PMID 39413500, 2024). "Overall, the changes in PEDF, MMP-2, and TGF-β2 levels in the aqueous humor of cataract patients are related to LOCS III classification, and the combined detection has an evaluation value for cataract development." (PMID 39413500, 2024). "Based on this, this study explores the changes of PEDF, MMP-2, and TGF-β2 levels in the aqueous humor of cataract patients and the correlation scores with cataract progression, to provide a reference for the clinical evaluation of cataracts." (PMID 39413500, 2024). "•PEDF levels were lower and MMP-2 and TGF-β2 levels were higher in cataracts." (PMID 39413500, 2024). "Interestingly, our results showed increased expression of MMP2 protein and MMP2/MMP9 activity in total proteins extracts and aqueous humour in 2-month-old K14E6 mice cataracts." (PMID 29888254, 2018). "Levels of MMP-2 and TIMP-2 in PEXG with cataract, PEXG after SLT and Cataract groups." (PMID 18939999, 2008). "In addition, the mRNA expression of MMP-2 and MMP-9 was in LECs over 121 times higher for MMP-2 and 274 times higher for MMP-9 in patients with glucocorticosteroid-induced cataracts than in those with non-glucocorticosteroid induced cataracts." (PMID 35457074, 2022). "Furthermore, the analysis of TGF-β-responsive genes by RT-qPCR showed increased expression of collagen (COL1A1), fibronectin (FN1), Snail, matrix metalloproteinase 2 (MMP2), and matrix metalloproteinase 9 (MMP9) in the cataracts of transgenic mice as compared to nontransgenic lens samples." (PMID 29888254, 2018).
cerebral aneurysms (7 papers, 2012 to 2024). "Other investigators, however, have documented elevated MMP-2 levels in vessel walls of ruptured and unruptured cerebral aneurysms and in patients who suffered ischemic stroke." (PMID 23691315, 2013). "We sought to determine the regulatory events associated with the expression of SPARC, MMP-2 and MMP-9 in ruptured and unruptured human cerebral aneurysms." (PMID 23516489, 2013). "The present study showed that SPARC expression in cerebral aneurysms is significantly correlated with MMP-2 and MMP-9 expression (P<0.05), and MMPs are by far the proteases that are the most closely related to the pathogenesis of intracranial aneurysms." (PMID 23516489, 2013). "In addition, pro-MMP-2 in vitro increased gelatinolytic activity in cerebral aneurysms." (PMID 26551785, 2015). "Sitosterol can treat cerebral aneurysms by reducing the expression of chemokines and inflammatory cytokines TNF-α, IL-8, IL-1β, IL-17, IL-6, and MMP-2/9." (PMID 33149752, 2020).
congestive heart failure (7 papers, 2013 to 2024). Failure of the heart to pump a sufficient amount of blood to meet the needs of the body tissues, resulting in tissue congestion and edema. "In the development of chronic heart failure, the activation of matrix metalloproteinase-2 (MMP-2) and matrix metalloproteinase-9 (MMP-9) plays a significant role, particularly in the early and late stages." (PMID 39201469, 2024). "Experimental evidence shows that MMP-2 is activated in I/R injury and congestive heart failure, and that pharmacological inhibitors of MMP activity or MMP-2 neutralizing antibody prevent LV remodeling and aid recovery of mechanical function." (PMID 31461499, 2019). "Clinical studies of congestive heart failure have correlated outcomes (survival) and extent of ventricular remodeling with circulating levels of MMP-2." (PMID 23874529, 2013).
hemorrhage (7 papers, 2013 to 2025). Loss of blood from the vascular compartment to the exterior or into nonvascular body space as a result of rupture or severance of the blood vessels. "It has been postulated that MMP-2 and -9 activation enabled the degradation of extracellular matrix component, causing damage to the stability and integrity of blood vessels, weakening the blood brain barrier and resulting in increased risk of hemorrhage." (PMID 31275742, 2019). "MMP-2 also exhibits a dual role, as excessive release of this enzyme can compromise the integrity of the blood-brain barrier, potentially leading to hemorrhage." (PMID 40342742, 2025). "It is believed that MMP-2 and MMP-9 (matrix metalloproteinase) expression levels interfere with hemorrhage." (PMID 38410133, 2024).
intervertebral disc degeneration (7 papers, 2013 to 2025). "The upregulation of lncRNA PART1 expression in the central nucleus pulposus tissue of patients with intervertebral disc degeneration can promote the intervertebral disc degeneration in nucleus pulposus cells by inhibiting the miR-93/MMP2 pathway." (PMID 34484336, 2021). "However, shRNA delivery can allow long-term studies to determine the functional role of genes relevant to intervertebral disc degeneration, such as MMP2." (PMID 23621950, 2013). "Furthermore, it was reported that UTI effectively inhibited the increased expression of MMP-2, MMP-3, NOS in degenerated NP cells induced by IL-1β in vitro which suggests that UTI may potentially be useful for clinical therapy of intervertebral disc degeneration." (PMID 27638499, 2016).
kidney cancer (7 papers, 2017 to 2025). Primary or metastatic malignant neoplasm involving the kidney. "In the literature, MMP2 is a matrix metalloproteinase associated with cancer cell invasion and metastasis of many cancers including kidney cancer." (PMID 36975533, 2023). "Furthermore, we showed that MTA1 is up-regulated in ccRCCs, which contributes to the migration and invasion of human kidney cancer cells by mediating the expression of MMP2 and MMP9 through the NF-κB signaling pathway." (PMID 33059651, 2020). "A study found that psoralen could slow the progression of kidney cancer by inhibiting the expression of MKI67, PCNA, MMP2 and MMP9 as well as the proliferation, invasion, and migration of kidney cancer cells HTB-47 and CRL-1932." (PMID 36627680, 2023). "MVs released from human kidney cancer stem cells contain angiogenic miRNAs and mRNAs that upregulate expression of VEGF receptor-1 (VEGFR1), VEGF and matrix metallopeptidase 2 (MMP2) in lung endothelial cells and stimulate formation of blood vessels, which contribute to lung metastasis." (PMID 29302403, 2017).
laryngeal carcinoma (7 papers, 2014 to 2022). Carcinoma that arises from the laryngeal epithelium. "MMP2 was mainly expressed in the cytoplasm and cell membrane in laryngeal carcinoma tissues." (PMID 34521883, 2021). "Whether AKR1B10 directly or indirectly promotes the occurrence and metastasis of laryngeal cancer through MMP2 remains to be further studied." (PMID 34521883, 2021). "Extracellular matrix degradation-related proteins, MMP-2 and MMP-9 were highly expressed in laryngeal carcinoma, overexpression of which was related to tumor migration and invasion." (PMID 35953439, 2022). "Among 87 laryngeal carcinoma tissues, 51 were AKR1B10+ MMP2+, 14 were AKR1B10− MMP2−, 5 were AKR1B10+ MMP2−, and 17 were AKR1B10− MMP2+." (PMID 34521883, 2021).
leiomyoma (7 papers, 2008 to 2026). A well-circumscribed benign smooth muscle neoplasm characterized by the presence of spindle cells with cigar-shaped nuclei, interlacing fascicles, and a whorled pattern. "Through ERK pathway, TNF-α promotes human leiomyoma smooth muscle cells migration and MMP-2 production." (PMID 41514933, 2026). "Alternatively, another work found MMP-1, MMP-2, MMP-3, and MMP-9 with higher activity of MMP-2 in leiomyoma compared to myometrium." (PMID 24163697, 2013). "MMP-2 activity was significantly higher in leiomyomas than normal myometrium, but its impact on endometrial bleeding remains unclear." (PMID 34640407, 2021). "In addition that MMP-2 was significantly increased in leiomyoma cells, Curcumae rhizoma was also reported to inhibit the expression of MMP-2 which could also contribute to its use in the treatment of UF." (PMID 35800452, 2022). "Here, we studied TEM1, MMP-2 and MMP-9 expression in 50 samples of uterine leiomyosarcoma (n = 25) and leiomyoma (n = 25) tissues." (PMID 36639546, 2023). "In contrast, only weak (median of 20 and 35 for TEM1 and MMP-2, respectively) or negative TEM1 (10 negative) and MMP-2 (18 negative) staining were seen in 25 leiomyoma tissues." (PMID 36639546, 2023). "Protein expression levels of MMP-2 and MMP-9 were evaluated in leiomyoma tissue." (PMID 34640407, 2021). "Since leiomyoma progression is related to increases in extracellular matrix (ECM) accumulation and matrix metalloproteinase (MMP), BHT could effectively increase ECM-related protein expression, as well as MMP-2 and MMP-9 protein expression." (PMID 34578952, 2021).
Lewis lung carcinoma (7 papers, 2011 to 2023). "Our results illustrated that YFTL exhibited anti-metastasis effect on Lewis lung carcinomas by attenuating the activities of MMP-2 and -9 via down-regulating Akt/ERK pathways." (PMID 30781674, 2019). "However, there is a small amount of evidence demonstrating the association among VEGF and MMP2 and MMP9 in Lewis lung carcinoma cells." (PMID 23226772, 2012).